SAMHD1 (SAM and HD domain containing deoxynucleoside triphosphate triphosphohydrolase 1)
Diseases named in the same sentence as SAMHD1 in open-access papers (continued):
Sharing a sentence is not in itself a finding about the gene and the disease.
infection (continued). "Interestingly, it was also found that in vivo infection of myeloid cells in infected animals occurred irrespective of expression of the SIV Vpx auxiliary protein known to counteract the antiviral host cell restriction factor SAMHD1 highly expressed in myeloid cells." (PMID 35622876, 2022). "The post-infection upregulation of UNG and SAMHD1 and the downregulation of dUTPase suggest a coordinated response to the invading virus." (PMID 36114511, 2022). "We then used RT-qPCR to probe the base line expression levels of key UBER enzymes (UNG, APE1, pol β, lig III, DUT) and the dNTPase SAMHD1 in AM and MDM prior to infection with HIV." (PMID 36114511, 2022). "SAMHD1 WT and KO 293T cells seeded in triplicates in 96-well plates were infected with SARS-CoV-2 (multiplicity of infection [MOI] = 0.1) or HCoV-OC43 (MOI = 0.1)." (PMID 35085552, 2022). "In HIV-C-infected DCs, an increase in TNT number was accompanied by a significantly higher productive infection, which, however, can be explained by the ability of HIV-C to circumvent SAMHD1 via phosphorylation at its T592 residue." (PMID 35204813, 2022). "Upon infection, type I IFN production leads to the upregulation of TRIM21 expression that directly binds to SAMHD1, promotes its polyubiquitination at K622 via K48 chains and ultimately its degradation." (PMID 34835003, 2021). "The findings found in the present study suggest that only SAMHD1 rs6029941 (A/G) polymorphism is not able to induce the progression and worsening of the infection, but it would act as a factor that could increase the proviral load and contribute to the appearance of symptoms." (PMID 32656092, 2020). "While SAMHD1 and IFN signaling counteract mainly viral replication and production of infectious particles, we think that aCDase protects macrophages from infection with HSV-1 immediately after the virus is taken up." (PMID 32165633, 2020). "Upon infection, the E3 ligase TRIM21 is up‐regulated in an IFN‐dependent manner to induce SAMHD1 degradation and to relieve virus restriction." (PMID 31797533, 2020). "In contrast, Vpx activity modestly enhances infection in CD57+ Tm cells, likely reflecting degradation of the SAMHD1 restriction factor." (PMID 32353080, 2020). "Direct docking of SAMHD1 to DCAF1 is essential for Vpx-mediated SAMHD1 degradation during human immunodeficiency virus 2 (HIV-2) and simian immunodeficiency virus (SIV) infections via the CRL4-DCAF1 ubiquitin ligase complex." (PMID 32244340, 2020). "In line with the results of single-cycle infection, HIV-2 carrying Vpx-S13A had lower replication capacity, presumably due to the persistent SAMHD1 expression." (PMID 31015445, 2019). "We used a recently developed synchronized infection assay that measures HBV cellular uptake to determine the effect of SAMHD1 on viral entry." (PMID 30918010, 2019). "Despite the extensive characterization of the effects of Vpx on macrophage infection/transduction and its interaction with SAMHD1, the alteration of HIV-1 early post-entry kinetics upon SAMHD1 degradation is yet to be analyzed." (PMID 30423802, 2018). "Three to 4 days after infection, cells were analyzed for co-expression of HIV-1 or SIV Gag and SAMHD1 by flow cytometry." (PMID 30656243, 2018). "SAMHD1 degradation by Vpx(+)VLP and Vpx(−)VLP was evaluated by Western blotting 24 h after VLP addition, and infection levels were evaluated by flow cytometry 48 h postinfection." (PMID 29764952, 2018). "It was proposed that SAMHD1 degrades incoming HIV-1 gRNA, thereby restricting infection and preventing innate immune sensing of viral nucleic acids." (PMID 29176984, 2017).
infection (continued). "To probe the reversibility of regulation of CDK1/2 and SAMHD1 in MDM, we changed serum 3 days before infection from unstimulating HS to stimulating FCS, and vice versa." (PMID 28122869, 2017). "Although infection and subsequent innate immune sensing in DCs is blocked by SAMHD1, HIV-1 maintains an additional SAMHD1-independent mechanism of suppressing DC maturation through downregulation of TLRs." (PMID 29176984, 2017). "The expression level of SAMHD1 is reduced in DCs from elite controllers; these cells mount enhanced IFN responses to infection and are superior in vitro in stimulating CD8 T cells." (PMID 27477283, 2016). "Stimulation of macrophages with a combination of IL-12 and IL-18 prevented or blocked productive infection by HIV-1 and the expression levels of SAMHD1, at both mRNA and protein levels, were increased in IL-12/IL-18 monocyte-derived macrophages (MDMs)." (PMID 27411355, 2016). "We assayed SAMHD1 expression in several relevant cell types in vitro, in response to interferon beta (IFNB1) treatment or infection." (PMID 26936683, 2016). "We further found that, like the type I interferon-induced cellular anti-viral proteins SAMHD1 and MX2, SFN treatment blocks infection after entry, but before formation of 2-LTR circles." (PMID 27093399, 2016). "In line with the complete depletion of SAMHD1 observed in Vpx-loaded VLP-treated MDDCs, infection was highest for these cells, exceeding 90%." (PMID 26208151, 2015). "Recently, SAMHD1 was identified in macrophages, DCs and resting CD4+ T cells and shown to block infection with HIV-1." (PMID 26121641, 2015). "In additional experiments, we compared effects of complement opsonization on SAMHD1 degradation and phosphorylation in DCs between HIV-1 and HIV-2 (expressing Vpx) as well as DC infection using differentially opsonized HIV-2 (VSV)." (PMID 26121641, 2015). "It is possible that the down modulation observed is mediated by the virus in an attempt to facilitate the establishment of infection, similar to that seen for APOBEC3G and SAMHD1." (PMID 24410916, 2014). "Conversely, ectopic overexpression of SAMHD1 reduced HIV-1 and SIV Δvpx infection of otherwise permissive cell lines." (PMID 23344558, 2012). "Therefore, we tested whether SAMHD1 changes localization upon HIV-1-GFP infection." (PMID 22691373, 2012). "Subsequent studies demonstrated that silencing SAMHD1 enhanced HIV-1 and SIV Δvpx infection of myeloid cells." (PMID 23344558, 2012). "PBMC from patients homozygous for SAMHD1 R164X as well as WT SAMHD1 were stimulated with interleukin 2 (IL-2) and PHA followed by subsequent infection with the replication-competent CCR5-tropic HIV-1 SF162." (PMID 22174685, 2011). "This suggested that SAMHD1 expression promoted S protein-mediated viral entry, which in turn facilitated infection of authentic SARS-CoV-2 and HIV-1-spike-Luc/ZsGreen but not ΔS-VRP(G)." (PMID 41280104, 2025). "Interestingly, SAMHD1 expression decreased Δψm in the absence or presence of HIV-1-Luc/VSV-G infection, although infection potentiated the reduction." (PMID 40434097, 2025). "SAMHD1 KO significantly hindered SARS-CoV-2 S protein-mediated viral entry in Calu-3 cells; however, once this barrier was bypassed by VSV-G pseudotyping, the single-cycle infection of SARS-CoV-2 replicon was restored." (PMID 41280104, 2025). "Immunoblot analysis showed more efficient degradation of SAMHD1 and TASOR with the Vpx-P41A mutant, suggesting that disrupting the Pro41 hydroxylation site enhances Vpx stability during infection, leading to more effective antagonism of host restriction factors and increased viral infectivity." (PMID 40522994, 2025). "HIV-1NL4-3 infection did not significantly induce PARP cleavage in SAMHD1 KO cells at 2, 4, and 8 dpi." (PMID 40434097, 2025). "By contrast, the protein levels of BCL-2, BCl-XL, BAX, BAK, BIM, and BID, as well as mRNA levels of BAX, were not affected by SAMHD1 expression or HIV-1NL4-3 infection of THP-1 cell lines." (PMID 40434097, 2025).
infection (continued). "To investigate the impact of IAV infection on SAMHD1 expression in A549 cells, we infected A549 cells with a varying multiplicity of infection (MOI) of IAV and collected cell samples at different time points for WB and RT-qPCR analysis to detect viral protein and SAMHD1 levels." (PMID 38287375, 2024). "However, in U937 cells expressing WT SAMHD1 (blue line), the addition of Vpx+ SIV-VLPs considerably increased HIV-1 replication and this effect was still apparent when Vpx was added 48 h after infection." (PMID 37127613, 2023). "The restriction assay directly compares replication in the presence and absence of SAMHD1 to calculate an infection ratio whilst not reporting on absolute infection levels." (PMID 37127613, 2023). "If this threshold dNTP level is not met, because SAMHD1 is reducing the dNTP pool, then infection will be restricted." (PMID 37127613, 2023). "To explore this hypothesis, we performed infection assays in CD4+ T cells using free viral particles and evaluated the transcriptional expression of the viral restriction factors SAMHD1, TRIM5, and APOBEC3G." (PMID 35802715, 2022). "Macrophages are largely refractory to infection by HIV-1 in the absence of Vpx due to the activity of SAMHD1." (PMID 33563288, 2021). "Overcoming SAMHD1 restriction in MDMs to reach equal infection levels with viruses containing and lacking Vpx reveals a novel function of Vpx in elevating innate immune responses." (PMID 33563288, 2021). "At equal infection levels, Vpx-containing viruses cause significantly higher ISG induction than their Vpx-lacking counterparts, even in the absence of SAMHD1." (PMID 33563288, 2021). "Also, infection with HSV-2 has been shown to reduce the expression levels of antiviral restriction factors, including SAMHD1, in DCs." (PMID 33801276, 2021). "The latent HIV-1 reservoir mainly resides in resting memory CD4+ T cells, but they are normally not the direct targets for infection, due to the blocks in reverse transcription, integration and host restriction by SAMHD1." (PMID 33835029, 2021). "No major differences were observed in SAMHD1 expression levels or viral titers after infection with VLPs at an MOI of 2 and/or by adding HCMV 24 h later." (PMID 32986788, 2020). "However, in response to infection, male mice exhibited higher expression levels of CXCL2 (KO, 1A3, and 6A2), SAMHD1 (1A0, 1A3), RSAD2, STAT1, and STAT3 (1A0), MYD88 and PSMB8 (1A3), BCL3, BCL10, CCRL2, IFITM2, RTP4, and ZFP36L1 (6A2), compared to females." (PMID 32670284, 2020). "Infection of this cell type by HPV16 resulted in decreased SAMHD1 expression while the absence of SAMHD1 during HPV16 infection resulted in hyperproliferation and increased viral replication." (PMID 32244340, 2020). "SAMHD1 expression was increased after AD169 infection at 1 dpi and persisted up to 6 dpi, whereas SAMHD1 upregulation by HCMV was severely affected in Vpx- but not ΔVpx-expressing cells." (PMID 32986788, 2020). "It should be pointed out that infection of MDMG with HIV-1 in the absence of SAMHD1 antagonism was inefficient." (PMID 33298546, 2020). "In addition, SAMHD1 supports viral replication in Zika (ZIKV) and Chikungunya (CHIKV) infections as well." (PMID 32244340, 2020). "Productive infection of primary DCs was shown to be limited due to the restriction of SAMHD1, which is not counteracted by non-opsonized HIV-1." (PMID 32922405, 2020). "As a complementary approach to determine whether SAMHD1 plays a role in infection restriction in the CD127+ Tm cells, we abrogated its activity with Vpx, an accessory protein from SIV and HIV-2 that degrades SAMHD1." (PMID 32353080, 2020). "Interestingly, when SAMHD1 is degraded experimentally, DCs are able to sense HIV-1 and to produce type I interferons in response to HIV-1 and lose their trans-infection capacity." (PMID 32181159, 2020). "SAMHD1 depletion effectively relieved this restriction and allowed HIV‐1 GFP infection." (PMID 32852081, 2020).
infection (continued). "To determine whether SAMHD1 restriction activity was dependent on the amount of viral input, we assessed the effect of SAMHD1 silencing on HCMV growth in cells infected with lower MOIs (0.1 or 0.05) and at a later time point of infection (6 dpi)." (PMID 32986788, 2020). "Early investigations sought to characterize the potential DNase and RNase activity of SAMHD1, proposing that the dNTPase binds to and degrades vRNA in MDMs and ultimately restricts infection without triggering the innate immune response." (PMID 32244340, 2020). "We recently illustrated that complement (C) coating of HIV-1 (HIV-C), as primarily found during the acute phase of infection before appearance of HIV-specific antibodies, by-passed SAMHD1-mediated restriction in DCs and therefore mediated an increased DC activation and antiviral capacity." (PMID 31178863, 2019). "We investigated whether HBV infection of Wt or Samhd1 KO cells induced the expression of APOBECs along with MxA and ISG20 following a 6-h synchronized infection." (PMID 30918010, 2019). "SAMHD1 inhibits the early steps of HIV infection by limiting the viral cDNA synthesis by depleting deoxynucleotide triphosphates (dNTPs) and SAMHD1 degradation by HIV-2 VPX give rise to enhanced infection of DCs and production of type I IFNs." (PMID 31867020, 2019). "Our infection experiments have not shown any perturbation in SAMHD1 expression levels, consistent with a previous report, which is unsurprising, given the key role of SAMHD1 in cccDNA formation." (PMID 30918010, 2019). "The effect was specific for DSB as DNA damage induced by UV light irradiation did not affect SAMHD1 phosphorylation and did not block infection." (PMID 29515139, 2018). "Despite these reports however, we observed that macrophages that are permissive to HIV-1 remain non-permissive to super-infection by SIVΔvpx which demonstrates that the antiviral environment created by SAMHD1 is not modulated by HIV-1." (PMID 30656243, 2018). "Strikingly, infection with HIV-1 in the presence of Vpx, which leads to degradation of SAMHD1, does not change the levels of RT products; the infection rates are comparable between G2/M and G1 phase." (PMID 29884836, 2018). "HIV-1 does not modulate the antiviral environment created by SAMHD1 such that HIV-1-infected macrophages remain restricted to infection by Vpx-deleted SIV." (PMID 30656243, 2018). "Collectively, these results indicate that HIV-1 undergoes macrophage infection without modulating cellular SAMHD1 or dNTP levels." (PMID 30656243, 2018). "While the mechanism for SAMHD1 evasion employed by SIV and HIV-2 centers on the Vpx protein, it is not known how HIV-1, which does not harbor a Vpx-like activity, evades SAMHD1 during macrophage infection." (PMID 30656243, 2018). "This has prompted investigators to suggest that HIV-1 RT has evolved to operate in a low dNTP environment thus enabling macrophage infection without the need to evade SAMHD1." (PMID 30656243, 2018). "At 12 h p.i., >90% of the cells exposed to the Vpx-carrying particles lacked a detectable SAMHD1 signal; these conditions were, thus, chosen for subsequent infection." (PMID 30423802, 2018). "Reduced expression of SAMHD1 and p21 in CD2low PBMC of HIV-1-positive patients could render these cells more permissive for infection." (PMID 28953327, 2017). "Unlike other restriction factors, where expression alone is typically sufficient to block infection, SAMHD1 antiviral activity is often not measurable in dividing cell lines." (PMID 29056936, 2017). "Intracellular expression levels of all RFs tested (SAMHD1, p21, RISP, Tetherin) did not reveal any differences in total PBMC potentially associated with HIV-1 control or a progressing course of infection." (PMID 28953327, 2017). "Critically, and as before, we observed preferential infection of MCM2‐positive cells from WT but not SAMHD1 negative cells." (PMID 28122869, 2017).
infection (continued). "Neither BMMC activation nor IFNα production were affected by loss of SAMHD1, cGAS, or STING upon infection with Sendai virus (SeV), which is sensed via the RIG-I pathway." (PMID 27477283, 2016). "SAMHD1 transcript levels were IFN responsive, increasing during acute phase infection and decreasing during a more quiescent phase, but generally remaining elevated at all post-infection time points." (PMID 26936683, 2016). "Moreover, a bona fide infection model, HepG2-NTCP, was used to elucidate the impact of SAMHD1 on HBV replication." (PMID 27229711, 2016). "The fact that R848 blocked the infection of monocytes with Vpx-containing virus suggests that SAMHD1 was not the mechanism by which R848 protected these cells from infection." (PMID 27905985, 2016). "In vitro, primary macrophages and astrocytes did not undergo significant changes in SAMHD1 expression during the course of long-term infection with HIV or SIV, although early changes were observed in SIV-infected astrocytes." (PMID 26936683, 2016). "Indeed, degradation of SAMHD1 by HIV-2 Vpx increased HIV replication in both macrophage types, minimizing the initial differences in infection (p = 0.12)." (PMID 27541004, 2016). "The RNase activity of SAMHD1 inhibits infection by several retroviruses, but not infection by a number of common non-retro RNA viruses." (PMID 26032178, 2015). "To date, efficient lentiviral transduction of DCs or their monocyte derived counterparts (MDDCs) required high multiplicity of infection (MOI) or the exposure to the HIV-2/SIV protein Vpx to degrade viral restriction factor SAM domain and HD domain-containing protein 1 (SAMHD1)." (PMID 26208151, 2015). "Vpr from two viral clades, typified by SIVagm and SIVsyk, is also able to target SAMHD1 for degradation, facilitating infection of some types of non-dividing cells." (PMID 25856754, 2015). "Together, these data suggest that a weaker induction of SAMHD1, and possibly of TREX1, might facilitate HIV-1 replication and contribute to accumulation of HIV-1 RT products in cDCs from EC after ex vivo infection." (PMID 26067651, 2015). "Pre-incubation of DCs with Roscovitine prior to HIV loading resulted in a complete inhibition of SAMHD1 phosphorylation (immunoblot) and a significant impairment in productive infection with HIV-C, while the low-level HIV-infection was not affected." (PMID 26121641, 2015). "Furthermore, depletion of SAMHD1 via expression of a stable shRNA led to a marked accumulation of EIAV genomic RNA at early time points post-infection, suggesting that EIAV infection is also controlled by SAMHD1." (PMID 26032178, 2015). "Intriguingly, double infection of CD4+ T cells occurred preferentially in memory CD4+ T cells—particularly the central memory (TCM) subset—but was not a consequence of SAMHD1-mediated restriction of HIV infection in naïve cells." (PMID 26559763, 2015). "There was a marked increase in SeV viral RNA levels, which peaked at 24 h post-infection; however, there was no significant accumulation of SeV RNA under SAMHD1-depleted conditions." (PMID 26032178, 2015). "Vpx enables infection of myeloid cells, including macrophage and dendritic cells, with HIV-2 and SIVmac viruses by inhibiting the recently identified macrophage restriction factor SAM domain HD domain-containing protein 1 (SAMHD1)." (PMID 24465411, 2014). "In addition, Q76A Vpx mutant was still able to substantially rescue IFN-treated MDDC infection, although it was unable to bind DCAF1 and induce SAMHD1 degradation." (PMID 24782834, 2014). "Knockdown of SAMHD1 led to a 7-fold increase in HIV-1 infectivity, which was completely rescued in the control siRNA cells by adding Vpx-VLPs to the cells 2 hrs prior to infection." (PMID 24485168, 2014). "Moreover, a Vpx mutant devoid of the C-terminus proline-rich region is still able to efficiently degrade SAMHD1 and to rescue HIV-1 in single-cycle infection of MDDCs, but does not support HIV-2 replication in MDMs or MDDCs." (PMID 24782834, 2014).